HTR7 (5-hydroxytryptamine receptor 7)
Description:
G protein-coupled receptor for 5-hydroxytryptamine (serotonin), a biogenic hormone that functions as a neurotransmitter, a hormone and a mitogen. Ligand binding causes a conformation change that triggers signaling via guanine nucleotide-binding proteins (G proteins) and modulates the activity of downstream effectors. HTR7 is coupled to G(s) G alpha proteins and mediates activation of adenylate cyclase activity.
Synonyms: 5-HT7
Tractability: Small molecule: an approved drug acts on it; a structure with a bound ligand is known; a high-quality ligand is known; it belongs to a druggable protein family. Antibody: UniProt places it where antibodies can reach, with high confidence; its Gene Ontology location is reachable by antibodies, with high confidence; UniProt predicts a signal peptide or a membrane-spanning region; the Human Protein Atlas places it where antibodies can reach. PROTAC: a small molecule that binds it is known.
Target class: Monoamine receptor; Family A G protein-coupled receptor; Small molecule receptor (family A GPCR); Serotonin receptor; Membrane receptor
Chemical probes: CHEMBL260994, PIMOZIDE, SB-258719 (high quality)
Safety:
Unwanted effects reported when the protein is acted on. In parentheses: how it was acted on, where the effect was seen, and who reports it.
decreased anxiety (inhibition, acute dosing; nervous system, immune; source: Lynch et al. (2017))
decreased body temperature (activation, acute dosing; nervous system, immune; source: Lynch et al. (2017))
decreased inflammation (activation, acute dosing; nervous system, immune; source: Lynch et al. (2017))
decreased pain (inhibition, acute dosing; nervous system, immune; source: Lynch et al. (2017))
decreased sleep (inhibition, acute dosing and activation, acute dosing; nervous system, immune; source: Lynch et al. (2017))
decreased/increased pain (activation, acute dosing; nervous system, immune; source: Lynch et al. (2017))
increased memory (activation, acute dosing; nervous system, immune; source: Lynch et al. (2017))
increased/decreased memory (inhibition, acute dosing; nervous system, immune; source: Lynch et al. (2017))
statin-related myalgia (source: ClinPGx)
Gene: Protein-coding gene on chromosome 10 (90,740,823 to 90,858,039, reverse strand). Ensembl gene ENSG00000148680.
Subcellular location: Cell membrane
Subcellular location (Human Protein Atlas): Nucleoplasm; Plasma membrane; Primary cilium; Vesicles
Pathways (Reactome):
Signal Transduction: G alpha (s) signalling events; RHOBTB3 ATPase cycle; Serotonin receptors
Gene Ontology:
Molecular function: G protein-coupled serotonin receptor activity; protein binding; neurotransmitter receptor activity; G protein-coupled receptor activity
Biological process: adenylate cyclase-activating serotonin receptor signaling pathway; blood circulation; chemical synaptic transmission; circadian rhythm; G protein-coupled receptor signaling pathway, coupled to cyclic nucleotide second messenger; G protein-coupled receptor signaling pathway; G protein-coupled serotonin receptor signaling pathway; smooth muscle contraction; vasoconstriction
Cellular component: cilium; plasma membrane; dendrite; trans-Golgi network membrane; membrane; synapse
Genetic constraint (gnomAD): Loss-of-function variants: 17 observed, 34.24 expected, observed/expected ratio (o/e) 0.5, 90% interval 0.34 to 0.75. The upper end of that interval is the gene's LOEUF score, 0.75, which puts it in group 3 of 6, group 1 being the genes least tolerant of losing a copy. Missense variants: 487 observed, 627.67 expected, observed/expected ratio (o/e) 0.78, 90% interval 0.72 to 0.84. Synonymous variants: 260 observed, 262.02 expected, observed/expected ratio (o/e) 0.99, 90% interval 0.9 to 1.1.
Homologues: Orthologues: chimpanzee HTR7 (99% identical), macaque HTR7 (90% identical), pig HTR7 (88% identical), rat Htr7 (88% identical), mouse Htr7 (87% identical), dog HTR7 (87% identical), rabbit HTR7 (87% identical), tropical clawed frog htr7 (70% identical), zebrafish htr7a (65% identical), guinea pig HTR7 (63% identical), zebrafish htr7d (63% identical), Drosophila melanogaster 5-HT7 (32% identical). Paralogues in human: HTR1B (28% identical), HTR1E (27% identical), HTR1F (26% identical), HTR6 (25% identical), HTR5A (24% identical), HTR2A (24% identical), HTR2B (22% identical), HTR2C (22% identical).
Diseases named in the same sentence as HTR7 in open-access papers:
HTR7 is named in the same sentence as 66 diseases in open-access papers, as found by Europe PMC text mining. Sharing a sentence is not in itself a finding about the gene and the disease. The quoted sentences say what the papers report.
depression (17 papers, 2008 to 2025). "The receptors 5HT2A and HTR7 have been linked to anxiety and depression and medications blocking these receptors act as antidepressants." (PMID 39680432, 2024). "One SNP in HTR7 was demonstrated to be associated with the response to antidepressants in both bipolar and unipolar depression." (PMID 38136791, 2023). "The serotonin receptors 5-HT1AR (also known as HTR1A) and 5-HT7R (also known as HTR7) have emerged as key players in stress-related disorders, particularly depression." (PMID 39279505, 2024). "For example, in a genetic mouse model of Fragile X syndrome, HTR7 activation is able to reverse long-term synaptic depression." (PMID 36335540, 2023). "Amisulpride is a DRD2/DRD3/HTR7 inhibitor that has been widely used in high doses to treat schizophrenia and in low doses for the treatment of depressive disorders." (PMID 37014697, 2023). "Among them, 5-HT1A (also known as HTR1A) and 5-HT7 (also known as HTR7) receptors have attracted considerable attention for their roles in mood disorders, such as depression and anxiety." (PMID 39279505, 2024). "Focusing on the serotonergic system—the foundation of the monoamine hypothesis of depression—we observed a significant reduction in 5-HT levels in the PFC following FMT, along with H3K27me3-mediated transcriptional repression of key genes including Tph2, Htr1d, Htr2a, Htr3a, Htr6, and Htr7." (PMID 41041075, 2025).
schizophrenia (13 papers, 2011 to 2025). A major psychotic disorder characterized by abnormalities in the perception or expression of reality. "HTR7 is a serotonin receptor that mediates impulsive behavior, and appears to have variants associated with schizophrenia." (PMID 21291537, 2011). "The HTR7 gene, a serotonin receptor, marked in red, is associated with schizophrenia." (PMID 38704507, 2024). "HTR7 genetic polymorphisms were found to have a relationship with schizophrenia according to GWAS." (PMID 38136791, 2023). "In particular, the HTR7 gene (5-hydroxytryptamine receptor 7) is a major neurotransmitter in the central nervous system, and a number of literatures related to bipolar and schizophrenia disorder are reported." (PMID 26075260, 2015). "This notion is supported in part by a prior result that HTR7 antagonism may have positive effects on schizophrenia-like cognitive deficits." (PMID 39977438, 2025).
Anxiety (6 papers, 2022 to 2025). Intense feelings of nervousness, tension, or panic often arise in response to interpersonal stresses. "We highlight here, for the first time, the concept of the HTR7 regulating brain inflammation in a context of WMI induced by perinatal exposure that models NDDs associated with prematurity, including memory deficits, anxiety-like-behavior, and deficits in social interactions." (PMID 36335540, 2023).
breast carcinoma (5 papers, 2009 to 2025). "The expression levels of HTR1A, HTR1B, HTR2A, HTR2B, HTR2C, HTR4, and HTR7 were significantly downregulated in highly malignant breast cancer types." (PMID 37795441, 2023). "C, TCGA breast cancer co-expression matrix for HTR7 PGG family genes and pseudogenes across tumor samples." (PMID 31029062, 2019). "However, when compared to normal breast tissue, HTR1A, HTR1B, HTR2A, HTR2B, HTR2C, HTR4, and HTR7 were suppressed in high malignancy breast cancer types, whereas they were highly expressed in low malignant breast cancer." (PMID 37795441, 2023). "D, Negatively correlated miRNAs for all members of the HTR7 PGG family in breast cancer." (PMID 31029062, 2019). "HTR7 mainly encodes the 5-HT7 receptor, and several studies have now shown that the 5-HT7 receptor is closely related to the development and progression of certain cancers, such as breast cancer, prostate cancer, non-small cell lung cancer, and laryngeal cancer." (PMID 41237175, 2025).
Cognitive impairment (5 papers, 2011 to 2025). Abnormal cognition is characterized by deficits in thinking, reasoning, or remembering. "Htr7+ Tregs can alleviate neuroinflammation and prevent neuronal damage by inhibiting CD8 T cell infiltration into the brain and suppressing excessive microglial activation, thereby improving LPS‐induced cognitive impairment in mice." (PMID 40501108, 2025).
colitis (5 papers, 2016 to 2025). Inflammation of the colon. "In contrast, in another study, it was observed that blockade of HTR7 in DSS-induced colitis or in IL-10−/− mice with the antagonist SB-269970 resulted in increased inflammation." (PMID 34502396, 2021). "In one study, the HTR7 was blocked in mice with DSS-induced colitis with the antagonist SB-269970." (PMID 34502396, 2021).
autism (3 papers, 2005 to 2023). Persistent deficits in social interaction and communication and interaction as well as a markedly restricted repertoire of activity and interest as well as repetitive patterns of behavior. "In 2014, Ciranna and Catania reviewed the involvement of the HTR7 in the modulation of neuronal and synaptic activity; mostly, they highlighted the association of HTR7 modulation with NDD deficits and autism-like phenotypes." (PMID 36335540, 2023).
laryngeal carcinoma (3 papers, 2024 to 2025). Carcinoma that arises from the laryngeal epithelium. "There are laboratory studies evaluating novel targets for laryngeal cancer such as the 5-hydroxytryptamine receptor 7, but further extensive analysis is required prior to translation to clinical care." (PMID 39429115, 2024). "For example, HTR7 promoted laryngeal cancer growth through the activation of the PI3K/AKT pathway." (PMID 39175079, 2024).
atopic dermatitis (2 papers, 2020 to 2022). "Genetic knockout of HTR7 completely abolished low dose of 5-HT-induced itch and partially reduced scratching in mouse model of atopic dermatitis." (PMID 32694980, 2020). "In mouse models with atopic dermatitis, knocking out TRPA1 and HTR7 reduced lesions and scratching in HTR7 and TRPA1 knockout mice with atopic dermatitis." (PMID 36613861, 2022).
bipolar depression (2 papers, 2022 to 2025). "Our network pharmacology‐based analysis suggests that lurasidone‐induced manic switching in bipolar depression may be associated with the modulation of HTR1A and HTR7, possibly through a mechanism similar to that of asenapine." (PMID 40202273, 2025). "This study revealed that lurasidone may regulate the serotonergic synapse signaling pathway by interacting with the identified core targets MAOB, HTR1A, HTR2A, HTR3A, SLC18A2, HTR1B, and HTR7 to induce treatment‐emergent mania in people with bipolar depression." (PMID 40202273, 2025). "While HTR1A, HTR2A, and HTR7 are known targets of lurasidone, MAOB, HTR3A, SLC18A2, and HTR1B were identified for the first time as targets of lurasidone potentially involved in its associated induction of acute manic episodes in people with bipolar depression." (PMID 40202273, 2025). "Our bioinformatics and computational analyses demonstrated that lurasidone may regulate the serotonergic synapse signaling pathway by targeting proteins such as MAOB, HTR1A, HTR2A, HTR3A, SLC18A2, HTR1B, and HTR7 to induce treatment‐emergent mania in people with bipolar depression." (PMID 40202273, 2025).
colon cancer (2 papers, 2017 to 2025). "Among them DGK1, HTR7, FLRT3, and ZBTB18 co-occurred with established regulators of human colon cancer pathobiology." (PMID 29344557, 2017).
migraine (2 papers, 2015 to 2025). "In addition to ADARB2 SNPs, the Norfolk Island pGWAS also found two SNPs in the glutamate receptor, metabotropic 7 (GRM7) gene and one SNP in the 5-hydroxytryptamine serotonin receptor 7 adenylate cyclase-coupled (HTR7) gene to be associated with migraine." (PMID 25916332, 2015). "Collectively, association of variants in these neurotransmitter-related genes ADARB2; GRM7; HTR7 connected by a common neurological pathway supports current theories of a perturbed serotonin and glutamate mechanism in migraine and in the Norfolk pedigree." (PMID 25916332, 2015).
Myalgia (2 papers, 2019 to 2021). "SNPs in the HTR3B and HTR7 genes were significantly associated with the myalgia score and may affect the development of myalgia in statin-treated patients." (PMID 33731122, 2021). "A candidate gene study in 195 statin-treated patients, of whom 51 experienced at least probable myalgia, found that rs2276307 and rs1935349 in the 5-hydroxytryptamine (5-HT, serotonin) receptor genes (HTR), HTR3B and HTR7, respectively, were significantly associated with myalgia score." (PMID 31861911, 2019).
brain injuries (1 paper, 2023). "We first evaluated the therapeutic potential of HTR7 in perinatal brain injuries by evaluating any modulation of its expression in the forebrain." (PMID 36335540, 2023). "The present study aims to evaluate HTR7 activation using LP-211 as a novel therapeutic compound to prevent perinatal brain injuries in our WMI model." (PMID 36335540, 2023).
cerebral infarction (1 paper, 2022). An ischemic condition of the brain, producing a persistent focal neurological deficit in the area of distribution of the cerebral arteries. "We have shown that deletion of Htr7 and Ccr6 in Tregs markedly reduced their ability to infiltrate and proliferate in the brain after cerebral infarction." (PMID 35911740, 2022).
colorectal cancer (1 paper, 2018). A primary or metastatic malignant neoplasm that affects the colon or rectum. "Two serotonin genes, Htr7 and Htr1b, were in common between the chemically-induced colorectal cancer mouse model and the previous mouse model exposed to E171 only." (PMID 29950665, 2018).
diffuse intrinsic pontine glioma (1 paper, 2019). A neuroglial tumor that arises from the middle portion of the brain stem. "HTR7, involved in neuroactive ligand-receptor interaction and the calcium signaling pathway, was reported to contribute to the development and progression of diffuse intrinsic pontine glioma." (PMID 31865908, 2019).
enteritis (1 paper, 2024). Inflammation of the small intestine. "Enteritis that is chemically induced by DSS or acetic acid has been associated with the activation of pro-inflammatory HTRs such as HTR2A and HTR7." (PMID 38398793, 2024).
glaucoma (1 paper, 2021). Increased pressure in the eyeball due to obstruction of the outflow of aqueous humor. "For the three HTRs (HTR1A, HTR1E, and HTR7), limited works have been undertaken to link them with glaucoma." (PMID 33874942, 2021). "These 13 glaucoma-associated genes can be divided into three functional groups: phototransduction-related genes (GNGT1, OPN1SW, PDE6A, PDC, CRX, CNGB1, GUCY2F), glutamate receptor (GR) genes (GRIN2B, GRIK3, GRIK4), and 5-hydroxytryptamine receptor (HTR) genes (HTR1A, HTR1E, HTR7)." (PMID 33874942, 2021).
glioma (1 paper, 2023). A benign or malignant brain and spinal cord tumor that arises from glial cells (astrocytes, oligodendrocytes, ependymal cells). "Metabotropic glutamate receptor 1 (GRM1), 5-Hydroxytryptamine (serotonin) receptor 7 (HTR7), and 5-Hydroxytryptamine (5-HT) receptor 2A (HTR2A) may play a role in glioma by participating in the interaction pathway of neuroactive ligand receptor interaction pathway." (PMID 36980973, 2023).
Hepatic steatosis (1 paper, 2022). Steatosis is a term used to denote lipid accumulation within hepatocytes. "Importantly, these results are supported by the expression of tissue-specific HTRs, such as HTR1B, HTR2A, HTR2B and HTR7, in the liver, the relationship of HTR2A with hepatic steatosis and that of HTR2B with hepatocyte proliferation." (PMID 35765850, 2022).
inflammatory bowel disease (1 paper, 2024). A spectrum of small and large bowel inflammatory diseases of unknown etiology. "Thus, our findings, along with other studies, raise the possibility that drugs that activate or inhibit HTR7 may be useful as immunomodulatory agents for treating human enteric infections as well as for managing inflammatory bowel disease." (PMID 39455564, 2024).
keloid (1 paper, 2025). An irregularly shaped, elevated mark on the skin caused by deposits of excessive amounts of collagen during wound healing. "Furthermore, the neuroactive ligand-receptor interaction pathway exhibited substantial changes, with 31 genes, including GRIN2D, HTR7, and CCKAR were upregulated and 44 genes downregulated in keloid tissues compared to normal skin controls." (PMID 41562114, 2025). "Additionally, 14 genes such as GRIN2D, HTR7, and CCKAR were found to be upregulated in the calcium signaling pathway, while 43 genes, including ATP2A1, ADCY8, and MCOLN3, were significantly downregulated, suggesting that calcium signaling plays a critical role in the pathology of keloids." (PMID 41562114, 2025).
melanoma (1 paper, 2020). A malignant, usually aggressive tumor composed of atypical, neoplastic melanocytes. "We mined expression data from the Cancer Cell Line Encyclopedia (CCLE) and found that some receptors particularly HTR7 have a high expression relative to the others in the human melanoma cell lines used in our system." (PMID 32085796, 2020).
myopia (1 paper, 2016). "Among the mRNAs targeted by differentially expressed miRNAs, there were several (Prkar1a, Rims2, Map2, Gabarapl1, Htr7, Add3, Erc1, Nlgn1) which were involved in synapse formation and function suggesting that synaptic function was one of the biological processes affected in form-deprivation myopia." (PMID 27622715, 2016).
osteoarthritis (1 paper, 2023). A noninflammatory degenerative joint disease occurring chiefly in older persons, characterized by degeneration of the articular cartilage, hypertrophy of bone at the margins and changes in the synovial membrane. "Alternatively, six of the top concordant genes (HTR7, TRAK1, LAMA4, HS6ST1, PDE4A, GPNMB) at 52 weeks have been documented in prior osteoarthritis literature." (PMID 37134114, 2023).
prostate carcinoma (1 paper, 2019). A carcinoma that arises from epithelial cells of the prostate gland. "We identified HTR7P1 pseudogene in the same PGG family as HTR7 gene, which is potentially regulated by hsa-miR-607 and hsa-miR-3654 in the TCGA prostate cancer dataset." (PMID 31029062, 2019). "As a result, parent genes HTR7, CNN2, MSN, and TAGLN2 are DE; they generate pseudogenes, which are specifically expressed in prostate cancer samples." (PMID 31029062, 2019).
psychosis (1 paper, 2020). "Five genes, DRD2, DRD3, HTR2A, OPRD1 and HTR7, are found shared by psychosis network and antipsychotics network." (PMID 32273551, 2020).
Salmonella Infections (1 paper, 2024). Infections with bacteria of the genus SALMONELLA. "We found that animals treated with the HTR7 antagonist phenocopied the conditional Tph2 KO mice in that they exhibited decreased levels of fecal IgA and increased susceptibility to Salmonella infection." (PMID 39455564, 2024). "Mice treated with the HTR7 antagonist did not display reduced gut motility but showed increased susceptibility to Salmonella infection, suggesting that gut motility is not the only factor that explains the elevated susceptibility to Salmonella infection in Tph2 KO animals." (PMID 39455564, 2024). "We also measured the effect of the HTR7 antagonist on IgA B cell differentiation and Salmonella infection, to use a non-genetic approach to probe the importance of serotonin-HTR7 interactions in vivo." (PMID 39455564, 2024).
stomach cancer (1 paper, 2024). "Research has identified serotonin receptors, specifically HTR2A, HTR2B, HTR3A, and HTR7, as potential targets for both the prevention and treatment of stomach cancer." (PMID 39766808, 2024).